FASN (fatty acid synthase)
Diseases named in the same sentence as FASN in open-access papers (continued):
Sharing a sentence is not in itself a finding about the gene and the disease.
breast cancer (continued). "Collectively, our findings identify FASN as a novel mediator of endocrine resistance in luminal B-like, ER+/HER2+ breast carcinomas that might be exploited as potential therapeutic target and biomarker of response to tamoxifen in the clinic." (PMID 33800852, 2021). "Moreover, the expression of FASN, carnitine perilipin-1 (PLIN1), and palmitoyltransferase-1A (CPT1A) are elevated in HER2-positive breast cancers." (PMID 33489906, 2020). "Lipid metabolism is a major determinant of therapeutic resistance, with fatty acid synthase (FASN) overexpression inducing resistance to various drugs, including adriamycin and mitoxantrone, in breast cancer cells and radiotherapy-resistant head and neck squamous cell carcinomas." (PMID 33022920, 2020). "They described that FASN overexpression correlated with better outcome in progesterone-negative cases of breast cancer patients." (PMID 32899149, 2020). "In breast cancer, FASN–PPARα functions as a negative feedback loop axis where PPARα activation is shown to suppress FASN expression through SREBP-1c inhibition." (PMID 32872164, 2020). "Given the involvement of the enzyme FASN in numerous tumor types, FASN inhibitors including C75, C93, epigallocatechin gallate, G28UCM, orlistat, Fasnall, GSK2194069, and GSK837149A have been evaluated in a mouse model of breast cancer." (PMID 32028963, 2020). "Additionally, fatty acid synthase (FASN), a critical lipogenic enzyme, is essential for EMT development in breast cancer." (PMID 32793598, 2020). "In addition, in breast cancer, like ADP, the FASN expression is correlated with the HER2 status and the subtype of the immunoprofiling classification, and in prostate cancer, the FASN expression is correlated with the AR expression." (PMID 32103349, 2020). "To date, the only FASN inhibitor to advance to clinical studies is TVB-2640, which has been shown to elicit promising responses across a variety of tumor types, including KRASMUT NSCLC, ovarian, and breast cancers." (PMID 32226926, 2020). "In addition, FASN inhibition showed cytotoxic effects in lung cancer and resensitized cells to chemotherapy, anti-EGFR and anti-HER2 therapies in breast cancer." (PMID 32438613, 2020). "Furthermore, the authors showed a strong inhibition of cancer cell proliferation in breast cancer cells and hepatocellular carcinoma cells when ACC and FASN were inhibited." (PMID 33302403, 2020). "We evaluated FASN protein expression in an HRG-overexpressing model of biologically aggressive, endocrine-resistant ER+ breast cancer developed in our laboratory by transducing MCF-7 breast cancer cells with a retroviral vector containing the HRG cDNA (MCF-7/HRG cells)." (PMID 33081219, 2020). "In addition to IDH, FASN in lipid synthesis and GLS1 in glutamine metabolism have been reported as targets for breast cancer and colorectal cancer, respectively, Sun and Yang (2020)." (PMID 32850862, 2020). "Similar to results with breast cancer cells, macropinocytic LNCaP cells, but not non-macropinocytic 22Rv1 cells, were also rescued from FASN inhibition by supplementation with necrotic cell debris." (PMID 32111826, 2020). "Because AKT is rapidly repressed in response to C75-induced blockade of FASN activity, our findings suggest a positive feedback regulation between FASN and autocrine prolactin expression via AKT-driven activation of the PRLR/JAK/STAT5 pathways in PR+ breast cancer cells." (PMID 33335078, 2020). "For instance, RAPA may synergise with FASN inhibitors, which induces cytotoxicity in ER/HER2+ breast cancer cells." (PMID 32899149, 2020).
breast cancer (continued). "The expression of fatty acid synthase (FASN), a key enzyme essential for the FAS, is elevated in breast cancer, and its upregulation appears to be connected with cancer development, recurrence and poor prognosis, suggesting the augmented FAS activity is important for breast cancer progression." (PMID 33489906, 2020). "Taken together, these results provide evidence for FASN activity as a biological determinant that enables HRG-driven hormone-independence and refractoriness to SERMs (tamoxifen) and SERDs (fulvestrant) in ER+ breast cancer cells." (PMID 33081219, 2020). "Gonzalez-Guerrico and coworkers showed that the inhibition of FASN led to the conversion of the ML phenotype to a non-malignant one by downregulating EMT markers in a breast cancer model." (PMID 30875891, 2019). "The aim of the present study was to investigate the synergistic effect of TQ alone and in combination with cyclophosphamide (cyclo), and to unravel the role of TQ in fatty acid synthase (FASN) mediated molecular signaling in Her2 + and Her2- breast cancer cell lines." (PMID 31030489, 2019). "Likewise, resveratrol, another FASN inhibitor, precluded the growth of the CSC population both in vitro and in vivo using a breast cancer xenograft model." (PMID 30875891, 2019). "Interestingly, immunoprecipitation of breast cancer cell extracts by OPG antibody revealed lipid metabolic enzyme, fatty acid synthase (FASN), which is a key enzyme of the fatty acid biosynthetic pathway." (PMID 30717356, 2019). "Breast cancer cells were shown to upregulate FASN to induce non-homologous end joining DNA repair which in turn counter-acted the genotoxic stress induced by chemotherapy and radiotherapy." (PMID 31769430, 2019). "We further demonstrated that miR-195 also targets genes involved in de novo lipogenesis, it inhibits cell proliferation, migration, and invasion by targeting FASN, HMGCR, ACACA and CYP27B1 thereby potentially opening new avenues for the treatment of breast cancer." (PMID 30932749, 2019). "In particular, in HER-2-enriched breast cancer, we noticed a strong LOX-1 overexpression as compared with other phenotypes, suggesting a possible involvement of FASN in modulating proliferative rate of this breast cancer cells suggesting a potential connection of LOX-1 in FASN-HER-2 axis." (PMID 30718451, 2019). "We recently made a novel observation that IGF-I regulates FASN abundance in non-malignant mammary epithelial cells and estrogen receptor (ER)-positive breast cancer cells." (PMID 30323899, 2018). "Similarly, siRNA-mediated reduction of BRCA1 in breast cancer cells resulted in a decrease in ACCA phosphorylation and an increase in FASN abundance." (PMID 30323899, 2018). "Consistent with this notion, breast cancer cells have been shown to synthesise up to 95% of their fatty acids regardless of exogenous supply and this is facilitated by upregulation of activity and abundance of fatty acid enzymes including ACCA and FASN." (PMID 30323899, 2018). "Understanding the role of FASN and IGFBP-2 in chemo-resistance could provide a novel target for improving the effectiveness of breast cancer treatment." (PMID 29088813, 2017). "We therefore investigated whether FASN inhibition modulated the MAPK signaling pathway, which has been repeatedly shown to sensitize breast cancer cells to E2." (PMID 28240737, 2017). "For HER2 breast cancer subtype, Pharmacologic FASN inhibitors were found to suppress p185(HER2) oncoprotein expression and tyrosine kinase activity in breast cancer overexpressing HER2, which shows the correlation between FASN and HER2 type breast cancer." (PMID 29322925, 2017). "In summary, our findings reveal an unanticipated ability of FASN-catalyzed endogenous lipogenesis to modulate the sensitivity of breast cancer cells to E2-dependent ERα signaling via regulation of non-genomic MAPK/ERα and AKT/ERα cross-talk." (PMID 28240737, 2017).
breast cancer (continued). "In this study, we found that 60 μM DHA, but not AA and OA, reduced p-SREBP-1, m-SREBP-1, and FASN protein expression in insulin or E2 stimulated human breast cancer MCF-7 cells." (PMID 29282029, 2017). "Based on our results presented so far, we predicted that breast cancer cells with constitutive MAPK hyperactivation would exhibit a more pronounced sensitivity to E2-stimulated, ERα-mediated transcriptional activity upon FASN blockade." (PMID 28240737, 2017). "Fatty acid synthase (FASN), the key enzyme for endogenous synthesis of fatty acids, is overexpressed and hyperactivated in a biologically aggressive subset of sex steroid-related tumors, including breast carcinomas." (PMID 28240737, 2017). "Interestingly, human breast cancer tissue samples displayed high expression of OPG, PGE2 and fatty acid synthase (FASN)." (PMID 27270654, 2016). "Here, we demonstrated several interesting findings in the context of paracrine action of the OPG rich breast cancer microenvironment that drives carcinogenesis via inducing and sustaining inflammatory COX-2 and lipogenic FASN in an invasive breast cancer setting." (PMID 27270654, 2016). "Abundant OPG, FASN and PGE2 expression were detected in breast cancer tissue sections." (PMID 27270654, 2016). "We reasoned that there might be crosstalk between OPG, FASN, and COX-2 that sustains the inflammatory pathways in breast cancer." (PMID 27270654, 2016). "MRNA levels of ACC and FASN were down-regulated after BRG1 knockdown in breast cancer cells but not in non-tumorigenic MCF-10A mammary epithelial cells." (PMID 27223259, 2016). "Collectively, the novel biological crosstalk between OPG, FASN, and COX-2 advocates for combinatorial drug treatment to block these players of carcinogenesis as a promising therapeutic target to treat highly invasive breast cancer." (PMID 27270654, 2016). "5-Amino-4-imidazole carboxamide riboside (AICAR), which is a pharmacological activator of AMPK, stimulated extracellular FASN release in breast cancer cells;26 therefore, we investigated the role of AMPK signalling in FASN and SREBP-1 expression in PCa cells treated with AICAR." (PMID 26878389, 2016). "Similarly, two enzymes catalyzing rate limiting steps upstream of FASN in de novo fatty acid synthesis, ACC and ACLY, are often dysregulated in cancer and have been proposed as breast cancer therapeutic targets." (PMID 27223259, 2016). "We have several interesting findings in the context of paracrine signaling in the OPG rich breast cancer microenvironment that drives carcinogenesis via inducing and sustaining inflammatory cycloxygenase-2 (COX-2) and lipogenic FASN in an invasive breast cancer setting (unpublished results)." (PMID 27072583, 2016). "Immunoblotting procedures confirmed the ability of U0126 and LY294002 to dose-dependently decrease FASN protein expression in CCN1-overexpressing breast cancer cells (data not shown)." (PMID 27713913, 2016). "The hypothesis is that blocking FASN, in combination with anti-HER2 signaling agents, would be an effective antitumor strategy in preclinical HER2+ breast cancer models of trastuzumab and lapatinib resistance." (PMID 26107737, 2015). "In addition, inhibiting FASN negatively affects the interaction between EGFR and HER2, which is a mechanism of trastuzumab resistance in breast cancer." (PMID 24866893, 2014). "As a control, we also measured FASN expression in the ER/HER2-negative MDA-MB-231 breast cancer cell line and determined that FASN was not expressed." (PMID 24866893, 2014).
breast cancer (continued). "Increased expression of FASN has been correlated with poor prognosis and chemo resistance in breast cancer cells and to our knowledge there is no report on the relevance of FASN levels in chemo sensitivity of HCC." (PMID 23613870, 2013). "Osthole could also down-regulate fatty acid synthase (FASN) expression and induce apoptosis in HER2-overexpressing breast cancer cells through inhibiting the phosphorylation of Akt and mTOR." (PMID 22662241, 2012). "Numerous studies have reported that acetyl-CoA carboxylase (ACCα) and fatty acid synthase (FAS), key limiting fatty acid synthesis enzymes involved in coenzyme A metabolic process (GO:0015936), are highly expressed in human breast cancer cell lines and breast carcinomas." (PMID 23281707, 2012). "The expression of two genes, CPT1 and FASN, that play key roles in fatty acid metabolism (lipolytic versus lypogenic) were evaluated at the basal mRNA level in the normal breast epithelial cell line 184B5 and in MCF-7 and MDA-MB-231 breast cancer cells." (PMID 21294903, 2011). "We found that FASN mRNA levels were significantly lower in both MCF-7 and MDA-MB-231 cells compared to 184B5 cells, suggesting that lipolytic processes were predominant in these particular breast cancer cell lines." (PMID 21294903, 2011). "When FASN activity was suppressed by either C75 and si-FASN or lapatinib through the downregulation of HER2-induced FASN phosphorylation, cell invasion was significantly inhibited in HER2-overexpressing SKBR3 and BT474 breast cancer cells." (PMID 21080941, 2010). "In summary, our data demonstrate that the inhibition of HER2 kinase activity by lapatinib results in decreased FASN tyrosine phosphorylation and reduced FASN enzymatic activity, which further downregulates HER2 signaling and results in suppressed breast cancer cell invasion." (PMID 21080941, 2010). "We hypothesized that FASN is directly phosphorylated by HER2, resulting in enhanced signaling and tumor progression in breast cancer cells." (PMID 21080941, 2010). "This novel finding indicates that the regulation of FASN activity by tyrosine phosphorylation may play an important role in the cell growth, invasion and metastasis of HER2-overexpressing breast cancer." (PMID 21080941, 2010). "Blocking both FASN and HER2 results in the synergistic suppression of breast cancer cell growth." (PMID 21080941, 2010). "FASN phosphorylation by HER2 plays an important role in breast cancer progression and may be a novel therapeutic target in HER2-overexpressing breast cancer cells." (PMID 21080941, 2010). "The current work extends these findings by demonstrating that resveratrol, a natural FASN inhibitor, suppresses both FASN expression and enzymatic activity, leading to apoptotic cell death across various breast cancer subtypes, independent of baseline FASN expression levels." (PMID 40733158, 2025). "Indeed, our study is the first to report a significant decrease in intracellular FASN expression and activity following resveratrol treatment in multiple breast cancer subtypes, with no notable differences observed among the subtypes in this regard." (PMID 40733158, 2025). "While FASN may be dispensable at high E:T ratios, at physiologically relevant low E:T ratios, the FASN lipogenic machinery appears to be essential for protecting HER2 + /PD-L1+ breast cancer cells from elimination by T-cells." (PMID 39349429, 2024). "Additionally, blocking FASN with EGCG has been found to significantly ameliorate the efficacy of cetuximab and pertuzumab in drug-resistant breast cancer, suggesting EGCG may synergize the antitumor effects of anti-EGFR and anti-HER2 therapies." (PMID 38348027, 2024). "Thus, targeting metabolic reprogramming, particularly fatty acid synthase (FASN) inhibition, in combination with standard HER2-targeted therapies represents a promising approach for overcoming resistance to anti-HER2 therapy in HER2+ breast cancer." (PMID 39123362, 2024).
breast cancer (continued). "FASN is associated with HER2 expression and may contribute to tumor growth, but it has no significant impact on the overall prognosis of breast cancer." (PMID 37124526, 2023). "Prostate cancer, liver cancer, and breast cancer had the highest levels of FASN expression, whereas kidney renal clear cell carcinoma (KIRC) and kidney chromophobe (KICH) exhibited the lowest levels of FASN expression, which is similar to the expression profile of FASN in normal tissues." (PMID 36555243, 2022). "Additionally, the FASN inhibitor cerulenin exhibits synergistic effects with docetaxel in HER-2-overexpressing and docetaxel-resistant SK-BR-3 cells, suggesting involvement of FASN in HER-2-induced breast cancer." (PMID 36059650, 2022). "In addition, the overexpression of FASN in adriamycin-resistant MCF7 breast cancer cells (MCF7/AdVp3000) has been suggested as a new target for chemoresistance and seems to be a poor prognosis indicator for breast cancer patients." (PMID 34829834, 2021). "Conversely, an AKT/MAPK-related constitutive hyperactivation of FASN gene promoter activity was unaltered in response to estradiol in non-endocrine responsive ER+/HER2+ breast cancer cells, and could be further enhanced by tamoxifen." (PMID 33800852, 2021). "Importantly, treatment with a FASN inhibitor impeded the estrogen-like tumor-promoting effects of tamoxifen and fully restored the anti-estrogenic activity of tamoxifen in ER+/HER2-overexpressing breast cancer xenografts." (PMID 33800852, 2021). "Acetyl-CoA carboxylase (ACC), fatty acid synthase (FASN) and 3-hydroxy-3-methyl-glutaryl-CoA reductase (HMGR) are potential targets of miR-195, whose ectopic expression regulates cellular triglyceride and cholesterol levels, leading to decreased proliferation and metastasis of breast cancer cells." (PMID 32547948, 2020). "Immunoprecipitation of FASN in breast cancer cells treated with and without Vermentino extract confirmed our hypothesis that UBC9 downregulation results in reduced SUMOylation complex formation." (PMID 32244364, 2020). "In order to make clear the way KDM5C regulates FASN expression, we analyzed the public ChIP-seq database which is processed by Cistrome analysis pipeline, and found a strong binding site of KDM5C in the promoter region of the gene locus of FASN in breast cancer cells." (PMID 32714863, 2020). "Moreover, FASN was found SUMOylated in human breast cancer tissues and cell lines, and lack of SUMOylation caused by SUMO2 silencing reduced FASN protein stability." (PMID 32244364, 2020). "Crucially, our study might help to validate FASN as a predominant therapeutic target in certain subgroups of poor prognosis luminal-type breast carcinomas that would not require the inhibition of multiple pathways to produce clinical benefit." (PMID 33081219, 2020). "Interestingly, in the presence of the FASN inhibitor C75, the ERα antagonist ICI 182 780, and the MAPK inhibitor U0126, E2-stimulated ERα-driven transcriptional activity reverts to the basal level seen in E2-depleted breast cancer cells." (PMID 28240737, 2017). "In MCF-7 human breast cancer cells, SREBP-1c mRNA levels and FASN mRNA levels are high, but SREBP-1a and SREBP-2 mRNA levels are low, and, after addition of epidermal growth factor (EGF), FASN and SREBP-1c mRNA levels are increased, while SREBP-1a and SREBP-2 mRNA levels are not." (PMID 29282029, 2017). "Based on these data, our results indicate that miR-15a-16-1, but not miR-497-195, could both reduce endogenous FASN expression and inhibit breast cancer cell proliferation." (PMID 27713175, 2016). "However, although all these miRNAs suppressed FASN 3′-UTR-mediated expression in reporter assays, only ectopic expression of miR-15a-16-1, but not miR-497-195, inhibited the endogenous FASN expression and reduced breast cancer cell proliferation." (PMID 27713175, 2016).